NLRP3 (NLR family pyrin domain containing 3)
Diseases named in the same sentence as NLRP3 in open-access papers (continued):
Sharing a sentence is not in itself a finding about the gene and the disease.
atherosclerosis (continued). "Small molecule inhibitors selective for NLRP-3, such as MCC950, OLT1177, and CY-09, have been shown to reduce IL-1β production and attenuate atherosclerosis progression in preclinical models." (PMID 37894840, 2023). "The classical NLRP3 inflammasome pathway is activated by two triggers, whose joint action drives ASC phosphorylation and produces ASC plaques to create atherosclerosis." (PMID 37836470, 2023). "In a pig model examining atherosclerosis and DM, increased levels of sterol regulatory element binding protein (SREBP)-1 in the aorta corresponded with an upregulation in NLRP3 expression." (PMID 37762961, 2023). "Thus, modulating NLRP3 inflammasome may be beneficial for managing atherosclerosis." (PMID 36768748, 2023). "Here, we review our current understanding of the role which NLRP3 inflammasome regulation plays in cardiometabolic diseases such as obesity, diabetes, non-alcoholic steatohepatitis (NASH), atherosclerosis, ischemic heart disease and cardiomyopathy." (PMID 37336361, 2023). "As TNF-α, NF-κB, NLRP3, and IL-1β are crucial genes in the formation of ASC plaques to formulate atherosclerosis, we evaluated their expression in the aorta by Q-PCR." (PMID 37836470, 2023). "Further, G-protein-coupled receptor 124 (GPR124), an orphan receptor, plays a significant role in the development and progression of atherosclerosis by activating nitrosative stress and NLR family pyrin domain containing 3 (NLRP3) inflammasome signaling." (PMID 36671648, 2023). "Accumulating evidence from basic research shows that PCSK9 promotes vascular inflammation through upregulating classical pro-inflammatory pathways involved in atherosclerosis, such as TLR4/MyD88/NF-κB and NLRP3 inflammasomes." (PMID 36291690, 2022). "Btk promotes the progression of atherosclerosis by participating in the Btk–p300–STAT1–PPARγ pathway and promoting a series of responses induced by ox-LDL and NLRP3." (PMID 35296647, 2022). "Atherosclerosis share several molecular mechanisms with BAV, including dyslipidemia and the activation of specific pro-inflammatory pathways (NLRP3 inflammasome and TRL4)." (PMID 36071494, 2022). "The initiation of NLRP3 inflammasome in endothelial cells under pathophysiological conditions may exacerbate endothelial weakness, prompting hypertension, obesity, diabetes, neuroinflammation, retinopathy, atherosclerosis, cerebrovascular accident and malignancy." (PMID 35528818, 2022). "Meanwhile, they drive various inflammatory-related diseases such as gout, atherosclerosis, silicosis, and even DILI by inducing aberrant activation of the NLRP3 inflammasome." (PMID 35810159, 2022). "Recent studies have shown that nucleotide-binding oligomerization domain-like receptor protein 3 (NLRP3) inflammasomes, which are activated by ox-LDL, aggravate atherosclerosis through caspase-1-induced IL-1β secretion." (PMID 36330745, 2022). "Consistent with previous findings in an atherosclerosis model, 4μ8C treatment led to a reduction of Casp-1 activity in the hearts of LCWE-injected mice, reflecting reduced NLRP3 inflammasome activation." (PMID 35167493, 2022). "We found that the protective effects of 3‐HB disappeared in Gpr109a−/− and NLRP3−/− BMDM cells, indicating that 3‐HB attenuates atherosclerosis via the Gpr109a–NLRP3 pathway." (PMID 33977048, 2021). "In experimental models of atherosclerosis, FGF21 has been demonstrated to exert anti-atherosclerotic effects by a reduction of NLRP3 related pryoptosis of endothelial cells." (PMID 33846498, 2021). "However, the aberrant activation of NLRP3 inflammasome plays a crucial role in the pathogenesis of several human diseases, such as cryopyrin-associated autoinflammatory syndromes (CAPS), type 2 diabetes (T2D), gout, atherosclerosis, and neurodegenerative diseases." (PMID 33350984, 2021). "Activation of inflammasomes, such as Nlrp3 and AIM2, can exacerbate atherosclerosis in mice and humans." (PMID 34395445, 2021).
atherosclerosis (continued). "In the present study, we identified a previously unidentified function of UCP1 in protection against vascular dysfunction and atherosclerosis, through its inhibition of MMP and mtROS-induced activation of NLRP3 inflammasome in PVAT." (PMID 34878840, 2021). "Elimination or inhibition of the NLRP3 inflammasome complex, including NLRP3, ASC, or IL-1β, displays a protective function ameliorating inflammatory responses and atherosclerosis progression." (PMID 34070553, 2021). "Second, the accelerated atherosclerosis in SCAPD443N mice is largely attributed to increased local vascular inflammation, which is mediated by activation of the NLRP3 inflammasome." (PMID 34094640, 2021). "In atherosclerosis, increased ROS and impaired OGG1-dependent DNA repair led to the activation of NLRP3 and plaque formation." (PMID 34403365, 2021). "Subsequent studies reported that melatonin induced mitophagy through the Sirt3/FOXO3a/Parkin signaling pathway, attenuated NLRP3 (NLR family pyrin domain containing 3) inflammasome activation, and prevented the progression of atherosclerosis." (PMID 32257551, 2020). "We present the data implicating the NLRP3 inflammasome as a signaling pathway that is both activated by HIV-1 infection and that drives the development of atherosclerosis in PWH." (PMID 32596261, 2020). "The activated NLRP3 inflammasome has been widely linked to a large number of diseases, and several experimental studies highlighted that atherosclerosis may not be intrinsically caused by the NLRP3 inflammasome, but is closely linked to and often aggravated by NLRP3 inflammasome activation." (PMID 33553222, 2020). "Additionally, high-quality research has shown that NLRP3 inflammasome activation is correlated with multiple chronic inflammatory diseases and metabolic disorders, including obesity, hypertension, diabetes, atherosclerosis, neuroinflammation, retinopathy, stroke, and cancer." (PMID 32948742, 2020). "NLRP3 is the most studied NLR due to its involvement in several pathologies such as Alzheimer’s disease, atherosclerosis, cancer or allergy." (PMID 31547225, 2019). "NETs activate NLRP3 (NOD-, LRR- and pyrin domain-containing 3) inflammasome and proinflammatory cytokine production in macrophages in SLE and atherosclerosis." (PMID 30616678, 2019). "We first observe that high-salt intake promotes atherosclerosis formation in the aortas of ApoE−/− mice, through inducing the expression of NFAT5, NLRP3, and IL-1β in endothelium." (PMID 31429763, 2019). "In atherosclerosis and DCM models, silencing NLRP3 or other inflammasome components by using different approaches showed overall beneficial effects." (PMID 29850631, 2018). "It has been proved that chronic inflammation of the arterial wall is a key element in the pathogenesis of atherosclerosis, and the NOD-like receptor pyrin domain containing 3 (NLRP3) inflammasome is conducive to the occurrence of the chronic inflammation." (PMID 27110561, 2016). "In conclusion, the present study demonstrates that P2X7R and NLRP3 are expressed at hight levels in foam cell-rich human coronary atherosclerotic lesion areas, and that P2X7R is involved in the progression of atherosclerosis in vivo and in vitro." (PMID 25761252, 2015). "Evidence from the present and previous studies suggests that, in atherosclerosis, oxLDL is the most likely candidate to upregulate P2X7R and activate the NLRP3 inflammasome." (PMID 25761252, 2015). "Developing inhibitors or agonists for key molecules such as NLRP3 inflammasome, ALKBH5, MTHFD2, or specific immunoproteasome subunits could lead to novel immune-based strategies for atherosclerosis, offering more precise and effective clinical treatments." (PMID 41562048, 2025). "Persistent NLRP3-GSDMD activation contributes to pancreatic β-cell apoptosis, IR in adipose and liver tissues, and vascular inflammation, promoting complications such as diabetic nephropathy, retinopathy, neuropathy, and atherosclerosis." (PMID 40427455, 2025).
atherosclerosis (continued). "Not only is the NLRP3 inflammasome essential for mediating host innate immune defense mechanisms and maintaining homeostasis, but it can also contribute to immunopathology in some diseases such as CAPS, atherosclerosis, multiple sclerosis (MS), and cancers." (PMID 40830103, 2025). "With the NLRP3 inflammasome being relevant in immune and non-immune cells of the vasculature and myocardium, modulation of low-grade chronic inflammation underlying atherosclerosis, coronary artery disease and remodelling in ischemic cardiomyopathy could be achieved with targeted NLRP3 inhibition." (PMID 39969632, 2025). "Cholesterol accumulation in macrophages due to a loss of ABCA1 and ABCG1 cholesterol efflux transporters triggers NLRP3 inflammasome activation and atherosclerosis exacerbation but not lysosomal damage." (PMID 40564905, 2025). "Targeting the NLRP3 inflammasome, a sensor of deleterious endogenous and exogenous stimuli, is a promising therapeutic strategy for mitigating pro-inflammatory signaling and CVD progression, particularly atherosclerosis." (PMID 41277959, 2025). "Knockdown of NLRP3 or inhibition of the ERK/p38 pathway effectively reversed the effects of HHcy on VSMC dedifferentiation, highlighting the therapeutic potential of SXBX in managing HHcy-induced atherosclerosis." (PMID 39898976, 2025). "Finally, mechanistic investigations revealed that vulnerable psEVs promoted endothelial inflammation and atherosclerosis partially through miR‐497‐5p delivery and UCP2 suppression to activate the ROS/TXNIP/NLRP3 pathway." (PMID 40391195, 2025). "Pharmacologic inhibition of NLRP3 in these mice reduced plaque size and endothelial adhesion molecule expression, supporting inflammasome-targeted therapies as potential protective strategies against CHIP-driven atherosclerosis." (PMID 41516113, 2025). "This suggests that NLRP3 mediated lipid-driven macrophage proliferation in established atherosclerosis independent of the inflammasome complex." (PMID 40956333, 2025). "In our model of established atherosclerosis (i.e., after 12 weeks on a high-cholesterol diet), 4 weeks of MCC950-induced NLRP3 inhibition led to a significant reduction in macrophage proliferation (Ki-67.+: 6.37 ± 0.8%, vs. 4.1 ± 0.59%, p = 0.03, and EdU: 3.3 ± 0.42%, vs. 1.65 ± 0.47%, p = 0.02)." (PMID 40956333, 2025). "Notably, components of the NLRP3 inflammasome, including NLRP3, ASC, and caspase-1, exhibit elevated expression within carotid atherosclerotic plaques, implying their involvement in atherosclerosis pathogenesis." (PMID 38248345, 2024). "In a murine macrophage model of atherosclerosis, another histone deacetylase, HDAC6, was shown to promote nicotine-mediated inflammation and pyroptosis via deacetylation of p65, and activation of NF-kB and NLRP3 transcription." (PMID 39529883, 2024). "In addition to NLRP3-mediated inflammation, the AIM2 inflammasome also played a role in atherosclerosis in relation to CH." (PMID 39682303, 2024). "Evidence for the driving role of NLRP3 and NLRP3-mediated IL-1β production in the progression of cardiovascular disease was demonstrated in the CANTOS study, a randomized placebo-controlled and world-wide study in 10,067 patients with atherosclerosis." (PMID 39188718, 2024). "Moreover, the NLRP3 inflammasome, a complex comprising the NLRP3 receptor, ASC adapter, and pro-caspase-1, plays a pivotal role in atherosclerosis development by catalyzing the maturation of caspase-1, which in turn generates IL-1β/IL-18 from pro-IL-1β/IL-18." (PMID 38919547, 2024). "This literature focuses on the anti-inflammatory effects of Canakinumab, but does not fully explore its direct effect on the NLRP3 inflammasome and how this effect affects the progression of atherosclerosis." (PMID 39717099, 2024).
atherosclerosis (continued). "Recent studies have suggested that low WSS promotes atherosclerosis by inducing the formation of neutrophil extracellular traps (NETs) through the Piezo1-HDAC2 pathway and triggering endothelial cell pyroptosis via the IKKε/STAT1/NLRP3 pathway." (PMID 39474371, 2024). "This study demonstrated that targeting the interplay between NLRP3 inflammasome activation and dysfunction of MQC could be a potential therapeutic strategy for atherosclerosis." (PMID 38812059, 2024). "While NLRP3 is a key regulator of inflammasome activation, there is increasing evidence that other inflammasome sensors, such as NLRC4 and AIM2, also play a role in atherosclerosis." (PMID 37175869, 2023). "We further confirmed that NLRP3 deficiency did not alleviate NAFLD and atherosclerosis after APNtreatment." (PMID 37198205, 2023). "Inhibiting diabetes-related atherosclerosis by raising eNOS levels and decreasing NF-κB and TXNIP expression in response to the priming signal from NLRP3 inflammasome activation, Biejiajian (BJJ), a traditional Chinese medicine, has lately exhibited promising results." (PMID 37175869, 2023). "Our study provides a new evidence that butyrate could ameliorate the progression of inflammation in atherosclerosis through regulating macrophage polarization via GPR43-related and HDAC/PPAR-γ/NF-κB/NLRP3/miRNAs signal pathways." (PMID 36888629, 2023). "Our results indicate that APN supplementation prevents atherosclerosis and NAFLD via NLRP3 inhibition in mice, and suggest that APN might be a potential therapeutic agent for the prevention of atherosclerosis and NAFLD." (PMID 37198205, 2023). "By employing pharmacological (inflammasome inhibitors) and genetic approaches (NLRP3-/- mice and VSMC specific TXNIP deletion mice), we aimed to determine the effect and molecular mechanisms of inflammasome activation on atherosclerosis and atherosclerotic plaque stability." (PMID 37284455, 2023). "The NLRP3 [NOD (nucleotide oligomerization domain)-, LRR (leucine-rich repeat)-, and PYD (pyrin domain)-containing protein 3] inflammasome is the key mediator of IL-1 family cytokine production in atherosclerosis." (PMID 37155118, 2023). "Another facet of atherosclerosis pathogenesis is the upregulation and activation of TLR4 and NLRP3 inflammasome and the nuclear transcription factor NF-kB as an extension of the endogenous host response to cholesterol efflux signaling misregulation, which is mediated by oxLDL and CCs." (PMID 37175869, 2023). "In agreement, NLRP3 activation in OSA patients has been shown to induce the release of the coagulation initiator tissue factor (TF), that promotes systemic coagulation, thrombosis, and atherosclerosis progression." (PMID 37175608, 2023). "Among them, NLRP3 inflammasome components NLRP3, ASC, caspase-1 are highly expressed in carotid atherosclerotic plaques, suggesting that they are related to the pathogenesis of atherosclerosis." (PMID 35647057, 2022). "It should be noted that NLRP3-dependent activation of IL-18 production is involved not only in the pathogenesis of AD and atherosclerosis." (PMID 36138973, 2022). "Indeed, the deleterious effect of TET2 knockdown can be reversed by treatment with the NLRP3 inhibitor MCC950, indicating the pivotal role of IL-1β/NLRP3 inflammasome in TET2 atherosclerosis-related signaling." (PMID 35663390, 2022). "Collectively, this study demonstrated that by suppressing NLRP3 inflammasome, BJJ might reduce atherosclerosis and improve the vascular endothelial cells function in diabetic ApoE−/− mice." (PMID 35692570, 2022). "NLR family pyrin domain containing 3 (NLRP3) inflammasomes, which are part of the innate community of nucleotide-binding oligomerization domain-like receptors (NLR), are another triggering factor for atherosclerosis." (PMID 36204564, 2022). "Additionally, activation of NLRP3 inflammasome provoked high mobility group box 1 secretion, promoting VSMC-derived foam cell formation and accelerating atherosclerosis." (PMID 36186576, 2022).
atherosclerosis (continued). "Although the role of NLRP3 in atherosclerosis has not been fullyestablished, several studies have shown that it modulates the early stages ofdisease development." (PMID 39076616, 2022). "In atherosclerosis, its synthesis is triggered by the uptake of cholesterol crystals by macrophages activating the NLR family pyrin domain containing 3 (NLRP3) inflammasome or by the binding of IL-1 family members to their receptor IL-1R resulting in a positive autocrine inflammatory feedback loop." (PMID 35600479, 2022). "The production of IL-1α is not reliant on NLRP3 activation, so lack of its key components would not affect atherosclerosis." (PMID 36082127, 2022). "Ablation of NLRP3 compromised VX765 role in suppressing vascular inflammation and atherosclerosis." (PMID 35641492, 2022). "Since IL-1α does not need NLRP3 activation to be generated, missing its key components would not affect atherosclerosis." (PMID 32648087, 2021). "However, little is known about the mechanistic link between ER stress, TXNIP/NLRP3 inflammasome activation, and UCP2 activity on coronary vascular dysfunction in atherosclerosis." (PMID 34326395, 2021). "The mechanism of MCC950 on anti-atherosclerosis mainly involved in inhibiting the step of NLRP3 inflammasome activation rather than its priming step." (PMID 34588488, 2021). "In aortas of patients with coronary atherosclerosis, the levels of the NLRP3 protein were much higher compared to individuals without atherosclerosis." (PMID 33535473, 2021). "Nlrp3 inflammasome is activated in advanced human atherosclerotic plaques, but the role of GsdmD in sterile inflammatory diseases such as atherosclerosis is not yet described." (PMID 34395445, 2021). "A study has reported that fatty-acid-mediated mitochondrial uncoupling facilitates NLRP3-independent interleukin 1α (IL-1α) release in vitro, but not that of IL-1β, and atherosclerosis development in vivo." (PMID 33807807, 2021). "Several studies verified that NAC could decrease ROS generation and further inhibit NLRP3 inflammasome activation, and NAC-mediated disease/disorder involved atherosclerosis, bladder damage, and podocyte injury." (PMID 34367189, 2021). "NLRP3 inflammasome, whose formation is triggered by mitochondrial damage and IRF3-signaling-induced endothelial inflammation also contributes to the progression of atherosclerosis." (PMID 34307357, 2021). "Besides, Salvianolic acid A also inhibits NF-κB mediated NLRP3 activation in aortic tissues in ZDF rats, and thereby alleviating atherosclerosis at early stage." (PMID 34631209, 2021). "In contrast to Nlrp3 inflammasome and IL-1β, the direct role of GsdmD in atherosclerosis is not yet clear." (PMID 34395445, 2021). "Also, we determine more in-depth underlying molecular mechanisms by which exercise training improves coronary endothelial function by regulating ER stress, TXNIP/NLRP3 inflammasome signaling cascades, and UCP2-regulated ROS generation in atherosclerosis." (PMID 34326395, 2021). "Higher levels of NLRP3 in ACS patients rather than CAD patients indicate that it is not only elevated in chronic atherosclerosis, but also in the acute phase of the atherosclerotic process." (PMID 34685553, 2021). "Although Zbp1 has not yet been studied as an atherosclerosis modifier, it has a role as a sensor of viral infections, in NLRP3 regulation after viral infection, and a role in necroptosis and inflammation via its effects on the RIPK1, RIPK3, and MLKL pathways." (PMID 35052410, 2021). "Therapeutic agents that directly inhibit the NLRP3 inflammasome, including the natural compound arglabin, colchicine, and the small molecule inhibitor MCC950, have been shown to ameliorate endothelial inflammation and atherosclerosis in preclinical studies." (PMID 35002720, 2021).